KRAS (KRas proto-oncogene, GTPase)
Diseases named in the same sentence as KRAS in open-access papers (continued):
Sharing a sentence is not in itself a finding about the gene and the disease.
pancreatic cancer (continued). "The development of pancreatic cancer requires both, acquisition of an oncogenic mutation in KRAS as well as an inflammatory insult." (PMID 39627248, 2024). "KRAS mutations are frequently observed in pancreatic cancer and other types of cancer, making KRAS an appealing target for therapeutic interventions." (PMID 39130630, 2024). "summarized the metabolic networks regulated by mutations KRAS in colon, lung, and pancreatic tumors, focusing on the co-occurring mutations and the tumor microenvironment." (PMID 38706597, 2024). "KRAS plays an important role in normal tissue signaling, and mutations in KRAS are present in more than 90% of pancreatic cancer cases." (PMID 39201782, 2024). "A KRAS mutation can be found in up to 90% of all pancreatic tumors, making it a promising therapeutic target." (PMID 39687047, 2024). "Another trial in accrual is a single-arm Phase 1 trial employing the same KRAS SLP vaccine for administration in patients identified as being at high risk of developing pancreatic cancer based on family history and germline mutation testing." (PMID 39329989, 2024). "Overall, KRAS G12C mutations are rare in cancers of the digestive tract and we only detected one case in a patient with pancreatic cancer." (PMID 38664720, 2024). "KRAS mutations affect cell cycle survival and metabolism, cytoskeleton and cell motility, and transcriptional programs, all of which play a role in early pancreatic cancer changes and its progression." (PMID 38730578, 2024). "Since KRAS mutations are the most common genetic alterations in pancreatic cancer, and are present in more than 90% of patients, several scholars have investigated the use of KRAS mutations in liquid biopsy." (PMID 39617822, 2024). "Given that G12D, G12V, and G12R represent over 90% of KRAS mutations in pancreatic cancer, an effective therapy for these cancers represents a significant unmet need." (PMID 38576709, 2024). "Machine learning algorithms confirmed that KRAS gene mutation, hyperlipidaemia, and pancreatitis are potential risk factors for pancreatic cancer." (PMID 39640479, 2024). "They identified and studied four specific KRAS-targeting T cells from a pancreatic cancer patient who had received a vaccine with mutated KRAS peptides." (PMID 38732150, 2024). "The KRAS G12D variant is responsible for pancreatic cancer and is a target for cancer drug development initiatives." (PMID 38794122, 2024). "In line with this, the SLC7A5 inhibitor JPH203 exhibited synergistic effects when combined with a KRAS G12D inhibitor in 3 pancreatic cancer cell lines carrying the KRAS G12D mutation." (PMID 39704172, 2024). "Therapeutic development of compounds targeting HER3, including patritumab deruxtecan, is expected for pancreatic cancer, which is often characterized by KRAS mutations." (PMID 39651731, 2024). "For example, KRAS mutation, the most frequently found driver mutation of pancreatic cancer, has also been frequently found in intraductal carcinoma." (PMID 38607041, 2024). "KRAS mutant allele-specific imbalance correlates with the progression to ACP, and G-CSF expression correlates with KRAS mutations in pancreatic tumors." (PMID 39231851, 2024).
pancreatic cancer (continued). "The Kirsten rat sarcoma (KRAS) oncogene is mutated in approximately 95% of all pancreatic cancer cases and acts as the primary regulator of all cellular proliferation pathways in up to 90% of these cases." (PMID 39329989, 2024). "There is a report that the profile of KRAS mutations in pancreatic cancer tissue is correlate with prognosis." (PMID 38277079, 2024). "A total of 25–30% of tumors with KRAS mutations are key drivers in lung, colorectal, and pancreatic cancers." (PMID 38607003, 2024). "In pancreatic cancer, mutated KRAS upregulates endogenous EGFR expression, and hyperactivation results in a transformation from acinar to ductal metaplasia." (PMID 38396679, 2024). "Our study reveals that degradation of KRASG12V abolished lung and pancreatic tumors in mice and caused a robust inhibition of KRAS-regulated cancer-intrinsic signaling." (PMID 39718828, 2024). "For example, KRAS mutants dominate the Ras mutational burden in pancreatic cancer and NSCLC, whereas NRAS is most mutated in melanoma and acute myeloid leukaemia." (PMID 39372214, 2024). "KRAS mutations lead to uncontrolled cell growth and are early events in pancreatic cancer development." (PMID 39409171, 2024). "Recent studies have evidenced that KRAS-driven lung and pancreatic cancer with KEAP1 or NRF2 mutations are highly dependent on glutaminolysis and are vulnerable to glutaminase inhibition." (PMID 38830868, 2024). "From a clinical point of view, there is a dire need to target those oncogenic KRAS variants that are more prevalent in pancreatic cancer, including KRAS G12D." (PMID 38892436, 2024). "Given the critical role of KRAS mutations in cancers such as colorectal and pancreatic tumors, these findings suggest possible new targets for therapeutic intervention." (PMID 39684787, 2024). "Pancreatic cancer is driven by oncogenic KRAS variants in more than 90% of cases, and even those cases with wild type KRAS often show alternative alterations that activate oncogenic signaling through the RAS/MAPK pathway." (PMID 38892436, 2024). "KRAS G12D was the most frequent mutation and was identified in 32.42% of pancreatic cancers assessed in the study." (PMID 38893220, 2024). "In orthotopic mice models, exosomes derived from MSCs carrying short interfering RNA effectively suppressed tumor growth through targeting KRAS G12D, the most common mutation subtype in pancreatic cancer." (PMID 39054529, 2024). "A meta-analysis performed on 2249 patients with pancreatic cancer and published in 17 articles showed that KRAS mutations predicted poor prognosis with lower overall survival." (PMID 38607041, 2024). "In a clinical study, the G12D mutation was noted to be the most prevalent KRAS mutant transgressor amongst pancreatic cancer patients, comprising 44.9% (115/256), and CRC patients, comprising 30.8% (45/146)." (PMID 39184150, 2024). "This therapeutic approach has attracted considerable interest as it involves KRAS mutations, which are found in approximately 90% of patients with pancreatic cancer." (PMID 38756774, 2024). "The prognostic significance of KRAS mutational status in unresectable pancreatic cancer was explored in a study analyzing plasma DNA samples from 91 patients." (PMID 38666907, 2024). "In the pancreatic cancer pathway, for example, mutation-activated KRAS signaling through RalGDS involves PA via phospholipase D1/2 (PLD1/2)." (PMID 39676871, 2024).
pancreatic cancer (continued). "This breakthrough holds a potential in the treatment of various tumors with KRAS mutations or over-activation, including the cases of pancreatic cancer recurring after surgery." (PMID 39130630, 2024). "Reported clinical impact of KRAS variant allele frequencies (VAFs) on survival in pancreatic cancer." (PMID 38610868, 2024). "We confirmed that KRAS gene mutation, hyperlipidaemia, pancreatitis, and pancreatic cysts are significantly correlated with an increased risk of pancreatic cancer." (PMID 39640479, 2024). "Despite the limitations, the case report highlights the potential efficacy of TCR gene therapy in targeting the KRAS G12D hot-spot mutation and inducing regression of metastatic pancreatic cancer, and therefore provides an important basis for future studies." (PMID 38756774, 2024). "This underscores the significance of determining the KRAS mutation status of pancreatic cancer patients to identify those who are more likely to benefit from comprehensive genomic profiling." (PMID 38732320, 2024). "Multivariable logistic regression indicated that kirsten rats arcomaviral oncogene homolog (KRAS) gene mutation, hyperlipidaemia, pancreatitis, and pancreatic cysts are significantly correlated with an increased risk of pancreatic cancer." (PMID 39640479, 2024). "KRAS mutations are selectively enriched in lung, colon, and pancreas cancers – the three deadliest cancers in the United States." (PMID 38800401, 2024). "Apart from the predominant subgroup of individuals with KRAS-mutated pancreatic cancer, focus has shifted to the KRAS wild-type population, particularly concerning molecularly guided treatments." (PMID 38732320, 2024). "As such, the association between KRAS mutations and macropinocytosis has been investigated mostly in relation to pancreatic cancer." (PMID 38891084, 2024). "In a combined phase I/II study, 38 patients, who had previously been administered treatment for metastatic KRAS G12C mutated pancreatic cancer, were given sotorasib 960mg once daily." (PMID 37366887, 2023). "Expectations for using ctDNA to detect KRAS mutations have been raised in the early diagnosis of pancreatic cancer." (PMID 36673023, 2023). "Meanwhile, BxPC-3 (non-KRAS mutated pancreatic cancer cells) showed resistance to KV treatment compared to KRAS-mutated pancreatic cancer cells." (PMID 37174108, 2023). "In pancreatic cancer cells carrying KRAS mutations, the activation of nuclear factor erythroid 2-related factor 2 (NRF2) leads to upregulation of glycolysis, increased glutamine uptake, and reprogrammed glutaminolysis." (PMID 37705755, 2023). "When injected into pancreatic tumor masses with the KRAS G12V mutation, the LODER-encapsulating siG12D (siG12D-LODER) significantly inhibits tumor growth in vivo." (PMID 38069255, 2023). "Ninety percent of patients with pancreatic cancer exhibit KRAS mutation, and KRAS is one of the most important driver genes for pancreatic cancer development." (PMID 37377917, 2023). "Patients with KRAS wild‐type disease and early‐onset pancreatic cancer (EOPC) harbored actionable mutations including BRAF, EGFR, ERBB2, and MAP2K1/2.PGVs in PALB2, BRCA2, and ATM were associated with high PDAC risk in the Chinese population." (PMID 36999792, 2023). "In the case of siRNAs, researchers have explored their potential in targeting critical genes in cancer, such as the use of siRNAs against the BCR-ABL fusion gene in chronic myeloid leukemia and siRNAs targeting KRAS mutations in pancreatic cancer." (PMID 37814270, 2023). "Studies of KRAS-mutated cell lines in lung and pancreatic cancers have revealed that different cell lines have different degrees of dependence on KRAS." (PMID 36675641, 2023).
pancreatic cancer (continued). "Mutations in KRAS are prevalent in pancreatic cancer, and hedgehog signalling is an important mediator of pancreatic cancer." (PMID 37957639, 2023). "Chronic pancreatitis is a risk factor for pancreatic cancer, and mutations in the proto-oncogene KRAS are found in nearly all cases of pancreatic cancer." (PMID 36835366, 2023). "KRAS gene mutations are present in more than 80% of pancreatic cancer cases at the time of diagnosis." (PMID 36975494, 2023). "The co-administration of MPT0E028 and mitogen-activated protein kinase (MEK) inhibitors has synergistic effects in KRAS-mutated and KRAS-wild-type pancreatic cancer cells." (PMID 36902253, 2023). "Neither of these alterations are currently therapeutically targeted, except for KRAS G12C mutations, which can be targeted with kinase inhibitors sotorasib and adagrasib but are rare in pancreatic cancer." (PMID 36975505, 2023). "KRAS, a GTPase family member, is mutated at a high frequency in pancreatic cancer and is permanently activated to continuously stimulate downstream effectors, notably PI3K and RAF." (PMID 37187730, 2023). "In this study, we discovered the effect of KV on mediating the PI3K-Akt-mTOR and Erk-RPS6K-TMEM139 signaling pathways in oxaliplatin-resistant AsPC-1 cells (AsPC-1 cells; KRAS-mutated pancreatic cancer cells)." (PMID 37174108, 2023). "For instance, KRAS mutations which are widely detected in pancreatic cancers and colon cancers mediate multiple key glycolysis enzymes (such as HK-I/II, LDHA and GLUT1) thus leading glucose metabolism reprogramming." (PMID 37187730, 2023). "In this study, the antiproliferative and antimetastatic activities of KV, a bisbenzylisoquinoline alkaloid, were elucidated in KRAS-mutated oxaliplatin-resistant pancreatic cancer cells (oxaliplatin-resistant AsPC-1 cells)." (PMID 37174108, 2023). "Pancreatic cancer is characterized by KRAS mutations that universally occur in over 90% of cancers during the initiation period." (PMID 36835437, 2023). "The driver mutations in the ctDNA of breast, colorectal, lung, and pancreatic cancers for the KRAS, PIK3CA, EGFR, and HER2 genes have been extensively studied by ddPCR assays." (PMID 37593116, 2023). "It is reasonable to conclude that the pure SCC in the present case metastasized from the previous pancreatic cancer because of its common KRAS mutation." (PMID 37773552, 2023). "Using cell free DNA somatic mutation analysis, KRAS mutation and copy number gain were associated to worse outcomes in pancreatic cancer." (PMID 37007070, 2023). "The let-7 family, which was shown to be downregulated in pancreatic cancer and inhibits KRAS, HRAS, and TRIM71, is associated with poor survival." (PMID 37686149, 2023). "Apart from its prognostic value, some studies have described the detection of KRAS mutations in circulating cfDNA as biomarker to monitor treatment response and identify early signs of resistance in pancreatic cancer." (PMID 37798621, 2023). "We confirmed the effectiveness of the risk score for predicting the prognosis of patients with pancreatic cancer in the cohort of KRAS mutations." (PMID 38268915, 2023). "The KRAS mutation is involved in most of the metabolic reprogramming pathways that occur in pancreatic cancer." (PMID 37685710, 2023).
pancreatic cancer (continued). "In gastrointestinal cancers and pancreatic cancers driven by KRAS/BRAF mutation, GLI-1 is over-activated." (PMID 37304485, 2023). "The current work demonstrated the feasibility of specifically targeting pancreatic cancer cells with the KRASG12D mutation via EVs that carry siRNA to target mutant KRAS." (PMID 37296864, 2023). "Rac activation, together with Cdc42 and myosin II, forms a key response to mechanical stress in KRAS-mutated pancreatic cancer cells, promoting cytoskeletal remodelling, contractility, and migration." (PMID 36175301, 2023). "In this study, we explored the anticancer efficacy and mechanism of KV in oxaliplatin-resistant pancreatic cancer cells and patient-derived pancreatic cancer organoids (PDPCOs) with KRAS mutation." (PMID 37174108, 2023). "Since mutant KRAS is a critical mediator of pancreatic cancer metabolism, we evaluated the association between KRAS mutations and LIPH expression." (PMID 37990271, 2023). "Mutations in the KRAS gene are commonly associated with various types of cancers, particularly colorectal, lung, and pancreatic cancers." (PMID 37764496, 2023). "Patient-derived pancreatic cancer organoids (PDPCOs) with KRAS mutations were treated with KV, oxaliplatin (OXA), and a combination of KV and OXA." (PMID 37174108, 2023). "Patients with KRAS wild‐type disease and early‐onset pancreatic cancer (EOPC) harbored actionable mutations including BRAF, EGFR, ERBB2, and MAP2K1/2." (PMID 36999792, 2023). "KRAS‐mutated tumors, representing most pancreatic cancers, have overactive G1‐S cell cycle signaling, which drives cellular proliferation and tumor growth." (PMID 37840530, 2023). "The study of KRAS mutations has greatly improved the understanding of the processes involved in the transformation, uncontrolled proliferation, and invasion of pancreatic cancer cells." (PMID 36765725, 2023). "Autocrine IGF1 signalling has recently been identified as an essential survival mechanism for quiescent cancer cells derived from murine pancreatic tumours, allowing for growth and apoptosis resistance in spite of mutations in KRAS or MYC." (PMID 37608096, 2023). "Initial progression to pancreatic cancer embarks from the cells harboring KRAS mutations engaging in networking with proinflammatory cytokines." (PMID 37444617, 2023). "There have been reports of sotorasib anti-cancer effects demonstrated in 8 of 38 individuals with advanced pancreatic cancer who have previously received treatment and had KRAS p.G12C mutation." (PMID 37444534, 2023). "We herein report a case in which pure SCC of the liver appeared after surgery for adenocarcinoma of the pancreatic head, and the homology of KRAS mutation revealed that the liver tumor was a liver metastasis of the pancreatic cancer." (PMID 37773552, 2023). "That same study demonstrated that ZNF154 circulating-free DNA (cfDNA) methylation discriminated cases from healthy donor plasma samples and outperformed KRAS mutation frequency as a biomarker in pancreatic cancer." (PMID 37254212, 2023). "The KRAS G12C mutation is also found in a small fraction of pancreatic cancers, and sotorasib has shown efficacy in pancreatic cancer in a phase I study." (PMID 37046493, 2023).